Y_RNA (Y RNA )
Gene: Miscellaneous RNA gene on chromosome 20 (36,668,559 to 36,668,670, reverse strand). Ensembl gene ENSG00000202255.
Homologues: Orthologues: chimpanzee Y_RNA (100% identical), macaque Y_RNA (97% identical). Paralogues in human: Y_RNA (85% identical), Y_RNA (83% identical), RNY1P5 (81% identical), Y_RNA (81% identical), Y_RNA (80% identical), Y_RNA (79% identical), RNY1P2 (78% identical), RNY1P6 (78% identical), Y_RNA (78% identical), RNY1P1 (77% identical), Y_RNA (77% identical), RNY1 (76% identical), and 94 more.